LEP (leptin)
Diseases named in the same sentence as LEP in open-access papers (continued):
Sharing a sentence is not in itself a finding about the gene and the disease.
Obesity (continued). "Novel missense mutation Lys36Arg (rs111650508) in exon 2 of LEP is observed in one subject with obesity in the study population." (PMID 36619235, 2022). "Although KKAy mice have been widely used in mouse model of obesity further assessment using another obesity model mice, e.g. leptin-deficient ob/ob mouse or leptin receptor deficient db/db mouse, can validate our results." (PMID 35949596, 2022). "The underlying molecular mechanism of celastrol anti-obesity and increase the leptin sensitivity can be attributed to Sirtuin 1(Sirt1), interleukin-1 receptor 1(IL1R1), protein tyrosine phosphatase (PTP) 1B (PTP1B), and T-cell PTP (TCPTP)." (PMID 35444532, 2022). "Obesity has a strong association with immune cell abnormalities, and adipose tissue produces and releases various adipokines (leptin, adiponectin, resistin and visfatin) and pro-inflammatory cytokines (TNF-α, IL-4, IL-6)." (PMID 36574392, 2022). "Central and peripheral leptin and insulin resistance are also key obesity pathologies that have been definitively linked to O-GlcNAcylation in the latter system." (PMID 36111295, 2022). "5-HT2C receptor stimulation by administration of selective agonists is known to induce a marked decrease in food intake, and knockout of the 5-HT2C receptor subtype in mice caused leptin-independent hyperphagia and hypoactivity, leading to obesity." (PMID 35215322, 2022). "Leptin was found to be an important link between obesity and cardiovascular risk, with paradoxically increased leptin levels in obese individuals." (PMID 35684070, 2022). "Leptin was associated with pre-pregnancy BMI class (obesity β = 0.227, p = 0.046), and markers of body composition, namely thigh circumference (β = 0.278, p = 0.017) and upper arm fat area (β = 0.212, p = 0.060); diet quality had no impact on leptin." (PMID 35406128, 2022). "who studied baseline leptin level and its changes in relation to weight loss in a similar population of children with obesity participating in an inpatient treatment program." (PMID 35769076, 2022). "While many co-morbidities are associated with both obesity and autoimmunity (e.g., aging, gut dysbiosis, enhanced platelet activation)—key pieces of data are needed to firmly connect these via a non-leptin dependent mechanism." (PMID 36479348, 2022). "Obesity-associated alterations in leptin and adiponectin are major contributors in the development of dysfunctional adipose tissue, characterised by unresolved inflammation." (PMID 34977280, 2022). "We also analyzed their association with biomarkers of obesity (adiponectin and leptin) and inflammation (interleukin-6 (IL-6) and interleukin (IL-10))." (PMID 35207221, 2022). "Obesity, insulin resistance, and inflammation are associated with a decrease of adiponectin and an increase of circulating leptin." (PMID 35529082, 2022). "The leptin deficiency causes less expenditure of energy and is associated with obesity but exceptionally in many individuals, who are obese, elevated leptin concentrations are found." (PMID 35388304, 2022). "In this study, we investigated the association of LRG1 with obesity markers, including leptin and other adipokines in adolescents (11–14 years; n = 425)." (PMID 35955698, 2022). "From a hormonal point of view, obesity is associated with endocrine disruption, especially involving adipokines, leptin, adiponectin, sclerostin and irisin, which play an important role in musculoskeletal metabolism." (PMID 36382751, 2022). "Initially, leptin was the first adipokine associated with obesity and thus it was the most studied factor in regard to the link between obesity and breast cancer risk." (PMID 36428526, 2022). "In turn, leptin deficiency or polymorphisms in the leptin pathways increase appetite and energy intake, ultimately leading to obesity." (PMID 35978633, 2022).
Obesity (continued). "It is well known that breast milk leptin content is directly related to maternal body mass index and maternal plasma leptin, suggesting an important role for breast feeding in women with increased adiposity to lessen the risk of obesity in their offspring." (PMID 36558383, 2022). "Variants rs10244329 and rs11760956 from the LEP gene were directly associated with classic obesity markers." (PMID 35741707, 2022). "Since obesity is a significant risk factor for PCa, and there is a correlation between levels of the obesity-associated hormone leptin and PCa development, here we investigated the functional relationship between leptin and miR-628 regulation in PCa." (PMID 35710817, 2022). "OSA is usually accompanied by asthma, and they have many common risk factors, such as intermittent hypoxia, inflammation, leptin, and obesity." (PMID 36551211, 2022). "Obese animals have been shown to have increased levels of leptin, the hormone encoded by the obesity (ob) gene." (PMID 34550535, 2022). "Adiponectin shows cardioprotective and anti-inflammatory effects, while leptin is associated with several obesity-related CVDs and with inflammatory activity." (PMID 36289903, 2022). "In conclusion, obesity and dyslipidemia synergistically exacerbate psoriatic skin inflammation, and metabolic-disorder-associated inflammatory factors, palmitic acid, and leptin activate epidermal keratinocytes in the presence of inflammatory cytokines." (PMID 35457132, 2022). "In individuals, levels of IL-6, leptin, and resistin show an increase in obesity and are inversely associated with low inflammation but can return with exercise." (PMID 35250869, 2022). "On the other hand, obesity is associated with increased serum leptin level, which prevents respiratory depression by increasing CO2 chemosensitivity during sleep in obesity." (PMID 35619739, 2022). "Several polymorphisms in humans that are attributed to an obesity phenotype have been identified in the LEP and LEPR genes: an A to G nucleotide change at position 19 in the 5 V-untranslated region." (PMID 35886710, 2022). "The contribution of the genetic variant rs7799039 in the leptin gene as a marker of obesity is contradictory." (PMID 35684517, 2022). "This variant has previously been reported to be association with elevated serum leptin levels, metabolic syndrome, hypertension and obesity." (PMID 35334523, 2022). "Our data indicate that in mice, nutritional status during the perinatal period is critical in determining the magnitude of the leptin surge, which in turn affects susceptibility to dietary obesity in adulthood." (PMID 34475504, 2022). "A homozygous missense mutation in exon 3 of LEP gene c.298G>A (p.Asp100Asn), resulting in asparagine substituting aspartic acid at codon 100, was associated with severe obesity in India." (PMID 35563103, 2022). "In this context, cytokines such as TNF-α are produced and act on hypothalamic neurons, resulting in the inhibition of leptin and insulin signaling systems, causing obesity." (PMID 36290695, 2022). "Other obesity-associated factors affecting the risk of breast cancer are increases in levels of pro-inflammatory cytokines and leptin, which increases aromatization, and decreased levels of the anti-inflammatory and insulin-sensitizing adiponectin." (PMID 36040641, 2022). "The common SNP + 19G/A (rs2167270) in the untranslated exon 1 of LEP showed a similar allele frequency in both obesity and control groups." (PMID 36619235, 2022). "The cytokine producing capacity of T cells also changes with obesity in the general population and obesity-associated inflammation is in part driven by a shift to Th1 and Th17 which is thought to be mediated by leptin." (PMID 35348641, 2022). "The SNV rs7799039 (G2548A) in the promoter region of the LEP gene was found to be associated with the obesity phenotype." (PMID 36005598, 2022).
Obesity (continued). "FasL + granulocytic MDSC are increased with obesity via leptin signaling, causing CD8 + T cell apoptosis and resistance to immunotherapy." (PMID 35752704, 2022). "Another biologically inactive form of leptin, caused by missense mutation p.Asn103Lys, has been linked to severe obesity." (PMID 35563103, 2022). "This is consistent with a previous study showing that leptin pathway reflects a key mechanism with modifiable effects underlying sleep disturbance and obesity in children." (PMID 35892989, 2022). "Differences described in terms of altered sites and targeted nucleotides require further studies to establish a genetic profile underlying the influence of LEP SNPs on obesity." (PMID 35563103, 2022). "Ob/ob mice are deficient of leptin and develop obesity with hyperphagia and hyperinsulinemia (Lindström, 2007)." (PMID 35851836, 2022). "Obesity is associated with inflammatory adipokines including leptin, resistin, lipocain 2, IL-6, TNF-α, IL-1β, and IFN-γ." (PMID 35626330, 2022). "Amongst several hormones being dysregulated in the course of obesity, leptin, a key bioactive peptide largely secreted from the white adipose tissue (adipokine), has a strong association with both obesity and reproduction." (PMID 36855701, 2022). "Leptin insufficiency and leptin resistance in depressed patients have been implicated as mediators of obesity in these patients, as do disruption of the circadian rhythm and neurotransmitter dysregulation." (PMID 35911267, 2022). "The commonly used leptin deficient (ob/ob) or leptin receptor deficient/leptin resistant (db/db) background has been commonly used to replicate obesity involvement in MAFLD." (PMID 36499091, 2022). "Accordingly, genetic mutations in leptin or the leptin receptor promote fat accumulation and obesity development with immune system dysfunction in humans." (PMID 35631195, 2022). "Hormones such as leptin, which is secreted by fat cells, and insulin were found to mediate the genetic association of obesity with pre-eclampsia." (PMID 35104295, 2022). "Here, we show that gut microbe-targeted inhibition of the trimethylamine N-oxide (TMAO) pathway protects mice against the metabolic disturbances associated with diet-induced obesity (DIO) or leptin deficiency (Lepob/ob)." (PMID 35072627, 2022). "Independently, setmelanotide and leptin have proven successful in obesity management of individuals with congenital deficiency in genes of the leptinergic–melanocortinergic pathway." (PMID 34815532, 2022). "Increasing findings report that obesity is strongly associated with the development of leptin resistance, which in turn plays a key role in the pathogenesis of T2MD, but the mechanism needs to be more elucidated." (PMID 35198097, 2022). "Chronic, morbid positive energy balance alters WAT functionality, renders it insulin-resistant, and induces its immoderate secretion of leptin, resulting in a loss of sensitivity of the hypothalamus to this hormone in obesity." (PMID 35741001, 2022). "Insulin resistance caused by obesity is related to the development of a chronic low-grade inflammatory state and the action of adipokines, such as leptin, resistin, TNF-α, IL-6, MCP-1, and CRP." (PMID 36262532, 2022). "In humans, certain single-nucleotide polymorphisms in this locus are associated with decreased circulating leptin levels and obesity." (PMID 34523036, 2022). "In the regression analysis model, leptin was positively associated with obesity markers and insulin resistance." (PMID 36355134, 2022). "To further confirm the association between Fetuin B and leptin in obesity, we established a mouse model of diet-induced obesity." (PMID 35896788, 2022). "Several studies indicate that the loss of hypothalamic insulin signaling and leptin can induce changes in energy homeostasis, excessive food intake (hyperphagia), and body weight gain, leading to obesity development." (PMID 35445066, 2022).
Obesity (continued). "It has been established that LEPR polymorphism is linked to obesity, insulin resistance, and dyslipidemia, and that serum leptin in PCOS women is elevated due to a high quantity of adipose tissue." (PMID 36522620, 2022). "As ginsenosides target the central nervous system (CNS), which regulates leptin sensitivity in the cerebral cortex to prevent obesity and decreases the risk of central inflammation in the hypothalamus." (PMID 36263142, 2022). "Leptin regulates adipose tissue mass through central hypothalamus mediated effects on food intake, and increased serum leptin levels in obesity are often associated with a failure of the feedback loop and central leptin resistance." (PMID 35335996, 2022). "In monogenic obesity, mutations have been mainly identified in LEP or its receptors mostly at the hypothalamus level." (PMID 35563103, 2022). "CLSs are hallmarks of obesity, and ≤90% of macrophages are localized within CLSs in obese Leptin-deficient (db/db) mice and obese patients." (PMID 35543703, 2022). "Certain adipokines, such as leptin and adiponectin, have also been implicated as mediators of the effects of obesity on the progression of thyroid cancer." (PMID 36389127, 2022). "Leptin has a strong positive association with obesity, is expressed at higher levels in metabolically unhealthy PWO and is negatively associated with being underweight and malnutrition." (PMID 35844529, 2022). "The pathogenic role of leptin in obesity-linked malignancies, such as endometrial cancer, is complex." (PMID 35053431, 2022). "It has been reported that low levels of antibody production are associated with obesity, where elevated levels of circulating leptin induce a diminished immune response, together with high levels of pro-inflammatory cytokines." (PMID 36152043, 2022). "Human studies using pedigree analysis demonstrated that leptin gene mutations and defects in the leptin receptor led to extreme hyperphagia and obesity." (PMID 35056647, 2022). "This offspring obesity has been linked to changes in both offspring gut microbiome and hypothalamic gene expression associated with metabolic regulation, including the leptin system." (PMID 36005607, 2022). "It is possible that immune imbalance associated with obesity and elevated leptin levels favor the expansion of different CD4+ T cell subsets associated with AA severity." (PMID 35734271, 2022). "In androgen receptor deficient (ARKO) mice, late-onset obesity and fatty liver, as well as insulin- and leptin-resistance have been reported which is restricted to males." (PMID 35025875, 2022). "Serial studies have reported that obesity development is closely related to the out-of-control leptin encoded by the obesity gene (ob)." (PMID 35774455, 2022). "We can postulate that obesity in midlife increases the risk of AD by promoting systemic inflammation and leptin resistance, which leads to brain neurodegeneration." (PMID 35563589, 2022). "In particular, obesity is associated with increased levels of Leptin involved in both innate and adaptative immunity and macrophage recruitment." (PMID 35543703, 2022). "Several mechanisms have been proposed to explain the associations between obesity and impaired cognitive function, including inflammation, elevated leptin, insulin resistance, neuronal degradation, and impaired brain metabolism or blood flow." (PMID 35686024, 2022). "Third, obesity is associated with chronic inflammation due to increased pro-inflammatory cytokines and leptin by adipocytes and immune cells, including elevated C-reactive protein, interleukin 6, and ferritin." (PMID 35945221, 2022). "Accordingly, leptin deficiency (ob/ob mice) and leptin receptor deficiency (db/db mice) animals spontaneously develop into obesity and/or type 2 diabetes." (PMID 36465655, 2022). "High levels of plasma leptin and adipokines are directly associated with the extent of obesity and have previously been shown to facilitate endothelial dysfunction." (PMID 35837388, 2022).
Obesity (continued). "Impaired leptin signaling is frequently observed in obesity and has been implicated in the development of T2D, with evidence leptin resistance and hyperleptinemia play a pivotal role." (PMID 35119166, 2022). "Although HFrDs have been implicated in obesity via impairment of leptin signaling in humans, several in vivo studies have invalidated these assumptions in mice." (PMID 35684051, 2022). "Leptin is a 16 kDa cytokine-like hormone encoded by the obesity gene on chromosome 7q31.3, which was first discovered in 1994." (PMID 36578551, 2022). "Increasing levels of circulating plasma leptin are typical for obesity and associated with a leptin-resistant state." (PMID 35586628, 2022). "A similar effect was observed for the missense recessive mutation in exon 3 of LEP gene c.350G>A (p.C117Y), leading to impaired protein function associated with severe obesity." (PMID 35563103, 2022). "As mentioned, in obesity there is typically a basal state of metaflammation associated with insulin and leptin resistance which derails if an acute inflammatory reaction becomes superimposed by infection." (PMID 35406000, 2022). "Dysregulated adipocytokines and adipokines in obesity, such as leptin, resistin, TNF, and IL-6, are associated with the vascular dysfunction process." (PMID 35883829, 2022). "Leptin, fasting insulin, and insulin resistance each mediated between 20% and 50% of the total genetically predicted association of obesity with pre-eclampsia." (PMID 35104295, 2022). "Since obesity is associated with the polypeptide hormone, leptin, and the glucocorticoid hormone, cortisol, studying them will prove vital in designing an approach to treating the condition." (PMID 35480480, 2022). "Plasma leptin is considered a risk factor for obesity and cardio-metabolic disease, but the link between serum leptin and renal function is still under evaluation." (PMID 36619557, 2022). "Compromised body homeostasis due to obesity is associated with unregulated immune responses and chronic systemic inflammation, involving inflammatory factors such as leptin." (PMID 35164764, 2022). "Several studies that have investigated the association of leptin and LepR with obesity patterns have indicated several limitations with confounding factors, such as environment, psychological state, food habits, etc.." (PMID 35886710, 2022). "Leptin resistance, i.e., decreased response to Leptin, contributes to the development of obesity associated with aging." (PMID 36274849, 2022). "Human obesity-associated variants in SRC-1 impaired leptin-mediated Pomc reporter activity in cells, predominantly through a dominant negative effect." (PMID 35137184, 2022). "According to the study authors, leptin is a potential cause of reduced sucrose sensitivity in obesity-induced individuals." (PMID 35334918, 2022). "A systemic review and meta-analysis study reported that physical exercise reduced IL-6, decreased leptin, and increased adiponectin levels, corresponding to a reduction of obesity-associated systemic inflammation." (PMID 36293943, 2022). "Obesity is related to increasing leptin and some inflammatory factors that are associated with low-grade inflammation." (PMID 36151575, 2022). "Among them, obesity-induced insulin resistance and increased leptin levels are known to be among the main causes of NAFLD." (PMID 35565930, 2022). "A deficiency of leptin or defects in the components of this signaling pathway can lead to obesity, one of the major risk factors of AMI." (PMID 36407428, 2022). "Obesity is a risk factor for pancreatic cancer presenting the increased plasma leptin level in and activating different signaling targets such as matrix-metalloproteinase-13 signaling resulting in increased angiogenesis." (PMID 37529006, 2022). "Obesity and its associated chronic inflammation were shown to increase the risk of obesity-driven breast cancer through leptin, adiponectin, estrogen, and several pro-inflammatory cytokines." (PMID 35884530, 2022).